CD4 (CD4 molecule)
Diseases named in the same sentence as CD4 in open-access papers (continued):
Sharing a sentence is not in itself a finding about the gene and the disease.
autoimmune disease (continued). "Considering that glycolysis has been shown to be involved in CD4+ T cell activation and inflammatory response, we proposed that elevated glycolysis may be intermediate between DNA accumulation and T cell-mediated autoimmune diseases." (PMID 39872301, 2023). "Against this background, to further investigate the function and phenotype of CD4+ Tregs lymphocytes, and to avoid such heterogeneity and disparity of results, an analysis of the Helios transcription factor by flow cytometry has begun to be included in clinical research into autoimmune diseases." (PMID 38203623, 2023). "Constitutively expressed on CD25+ CD4+ regulatory T cells and is upregulated in all subsets of T cells upon activation;Signaling may promote anticancer and anti-infective immune responses, but may also be a driver of autoimmune diseases." (PMID 36675020, 2023). "The naïve CD4+ T cell compartment differentiates into effector and regulatory subsets of Th cells in various pathophysiological conditions, contributing to the development of various diseases and modulating tissue inflammation, particularly in autoimmune diseases." (PMID 38137450, 2023). "KC;iASPPΔ8/Δ8 pancreatic neoplasias had increased infiltration of Treg cells and CD8 cells, but not CD4 cells, suggesting that as in autoimmune disease, iASPP deficiency promotes Treg cell infiltration over conventional CD4 T cell infiltration in pancreatic neoplasia." (PMID 36746936, 2023). "On the contrary, increased numbers of another distinct subset of CD4+ T cells, Treg cells, exert suppressive effects in autoimmune diseases and allograft rejection, whereas a decreased number of these cells could enhance the immune response to cancers and chronic infections." (PMID 36005179, 2022). "CD4+CD25+ regulatory T (Treg) cells that express the transcription factor forkhead box protein 3 (Foxp3) are critical for maintaining immune homeostasis and preventing autoimmune disease and tissue damage caused by excessive or unnecessary immune activation, including autoimmune kidney diseases." (PMID 35251009, 2022). "Especially CD4 T cells are crucially involved in autoimmunity: first, during the initiation phase, because they lose their tolerance towards self-peptides, and second, by the subsequent ongoing presentation of self-peptides during the active autoimmune disease." (PMID 36458004, 2022). "In HLA class II-associated autoimmune diseases, the lack of a defined target cell and differential antigen processing in different antigen-presenting cells complicate identification of the HLA restriction of autoreactive TCRs from CD4+ T cells." (PMID 36700227, 2022). "Interestingly, CD28 also seems to play a central role in the regulation of IFNγ production, since several studies reported that CD4+ CD28- T cells secrete large amounts of IFNγ and have been associated with Th1-driven autoimmune diseases such as multiple sclerosis of rheumatoid arthritis." (PMID 35321714, 2022). "Since EAU is a T cell-mediated autoimmune disease, we investigated whether melatonin could influence CD4 + T cells activation and function, and found that the expression of the T cell inhibitory receptor, programmed cell death protein 1 (PD-1), was significantly increased after melatonin treatment." (PMID 35624485, 2022). "In addition, LEP levels were observed to be positively associated with CD4+ Th17 circulating percentage in patients diagnosed with autoimmune disease as Hashimoto’s thyroiditis and negatively with CD4+ CD25+ regulatory cells observed in relapsing-remitting multiple sclerosis (RRMS) patients." (PMID 36291602, 2022). "Moreover, concomitant stimulation of ß1-3-ADRs together with a B cell receptor (BCR)/TLR9 stimulus clearly enhances the anti-inflammatory potential of Bregs to suppress CD4 T cells, a crucial population in the pathogenesis of autoimmune diseases, like rheumatoid arthritis (RA)." (PMID 35073310, 2022).
autoimmune disease (continued). "Th17 cells (CD3+CD4+IL-17+) which are part of the immune system and emerge next to Th1 (CD3+CD4+INF-y+) and Th2 cells (CD3+CD4+IL-4+) from naive T helper cells, play an important role in protection against pathogens and are importantly implicated in the pathogenesis of autoimmune disorders." (PMID 35025939, 2022). "In addition, the treatment has decreased the levels of different types of exosomes with a particular interest in the HLA-DRDPDQ exosome, which plays an important role in presenting the MHC class II molecules to CD4+ T cells for rejection of organ transplantation and autoimmune diseases." (PMID 35203441, 2022). "Interestingly, increased USP16 levels, a deubiquitinase required for chromosomal segregation in mitosis, were observed in peripheral CD4+ T cells from patients with distinct autoimmune diseases and T cell-specific USP16 knockout mice showed a reduced severity of experimental autoimmune encephalitis." (PMID 34889895, 2021). "Thus, regulation of CD4+ T cells is a common denominator that could both prevent unwanted maternal immune responses against the fetus, and also explain improvement of autoimmune diseases during pregnancy." (PMID 34054852, 2021). "One small retrospective study revealed that CD4+ T cell count < 200/μL in kidney transplant recipients was a poor prognostic factor for PCP infection, and another showed that CD8+ T cell count < 160/μL was strongly associated with mortality in autoimmune disease patients with PCP." (PMID 33985440, 2021). "The IRF4-deficient T cells exhibit reduced capacity to induce expansion of T-helper subsets that cause autoimmune disease, suggesting that an intrinsic function of IRF4 in CD4+ T cells may be to sustain robust proinflammatory responses required to confer protection from pathogen." (PMID 33803441, 2021). "Likewise, in myasthenia gravis, an autoimmune disease regulated by CD4+ T-cells, which recognize the peptide epitopes p195–212 and p259–271 of the human acetylcholine receptor alpha-subunit, single amino acid mutations are able to inhibit myasthenia gravis autoimmune responses in mice." (PMID 33467522, 2021). "Additionally, the role of vitD supplementation for prevention or treatment of autoimmune diseases in general is supported because CD4+ T-cells are driving target organ destruction in autoimmune diseases and many of the autoimmune loci are shared by multiple autoimmune diseases." (PMID 34744990, 2021). "Therefore, pharmacological inhibition of P2Y10 in CD4 T cells might be a new strategy for the treatment of autoimmune diseases." (PMID 34815397, 2021). "Type 1 diabetes (T1D) is an organ-specific autoimmune disease characterized by severe autoimmune destruction of insulin-secreting pancreatic beta cells, especially by the combined actions of different immune cells, such as CD4 and CD8 conventional T cells with specificity for islet autoantigens." (PMID 34054801, 2021). "In contrast, the abundances of the genera Odoribacter and Desulfovibrio are increased in several autoimmune diseases, including rheumatoid arthritis, ankylosing spondylitis, and inflammatory bowel disease, likely due to an increased level of IL-17 and number of CD4+ Th17 cells." (PMID 34824318, 2021). "By creating such a pro-inflammatory microenvironment, CD4 CTL may favor their own persistence and expansion, and that of other potentially pathogenic TH cells, thereby contributing to pathogenic responses in autoimmune disorders." (PMID 34073458, 2021). "Moreover, in some autoimmune diseases, such as RA, and Granulomatosis with Polyangiitis, research revealed the correlation of CD4+ CTLs expansion and CMV infection, indicating that CMV infection may play a role in CD4+ CTL-mediated damage." (PMID 33603736, 2020).
autoimmune disease (continued). "Regulatory T cells (Treg), a subset of CD4+ T cells, play a significant role in regulating the immune response as well as maintaining self-produced antigen recognition by suppression of the activation and expansion of self-reactive T cells, which prevents autoimmune disease." (PMID 32824563, 2020). "Autoimmune uveitis is considered to be a T helper cell mediated autoimmune disease and in the study reported here, we found that A20 expression was decreased in CD4+T cells from active BD patients, supporting the hypothesis that A20 plays an important role in the pathogenesis of BD." (PMID 33613524, 2020). "Since in the context of autoimmune diseases, a large percentage of CD4+ T cells may be killed via TNF-related apoptosis-inducing ligand (TRAIL) or perforin and granzyme B, leading to CD4+ T-cell exhaustion, it is tempting to hypothesize that these mechanisms operate to promote tumor development." (PMID 33138017, 2020). "Determining how differentiation and survival of different subsets of memory CD4+ T cells in autoimmune disease conditions are affected by factors such as cytokine milieu and the presence of autoantigens may lead to potential new avenues for treatment of disease progression and relapses." (PMID 32106536, 2020). "A combination of cellular, molecular and in vivo approaches reveals that the non-classical MHC class II chaperone DO controls CD4 T cell thymic selection; its absence leads to susceptibility to two murine autoimmune diseases, collagen-induced arthritis and experimental autoimmune encephalomyelitis." (PMID 32069316, 2020). "Consequently, we developed an experimental model for the generation of autologous antigen-specific vitD3-tolDC and T cells from healthy donors, using an immunogenic peptide presented via class II MHC with the aim to reproduce antigen presentation in the context of CD4+-mediated autoimmune diseases." (PMID 33552054, 2020). "Therefore, n-3 PUFAs could be used to suppress the unwanted hyperactivation of both CD8+ and CD4+ T cells during infections and autoimmune diseases." (PMID 32545480, 2020). "However, it remains elusive whether DH can directly regulate CD4+ T cell biology and hence ameliorates the development of CD4+ T cell–mediated autoimmune disease." (PMID 33117376, 2020). "In addition, it is demonstrated that CD4+CD25hi Tregs from patients with autoimmune diseases such as, Multiple Sclerosis (MS), Polyglandular syndrome type II, Myasthenia gravis or Rheumatoid Arthritis (RA) have impaired functions compared to Tregs from healthy individuals." (PMID 33519807, 2020). "Anomalous autoreactive responses of CD4+ T helper cells, such as Th1 cells producing IFNγ 2 and Th17 cells producing IL‐17,47, 48, 49, 50, 51, 52 are tightly correlated with the clinical severity and progression of several autoimmune diseases, clinically and experimentally." (PMID 33135395, 2020). "Lowered levels of chromosome X contact in SLE CD4+ T lymphocytes may result in increased expression of immune-related genes on the X chromosome leading to dysfunctional immune cells and increased propensity for autoimmune disease development in XX cells." (PMID 31142749, 2019). "We identified the similarity of methylation profiles across these diseases and the common hypomethylation signature of type I IFN-related genes in CD4+ T cells of GD/RA/SLE/SSc patients, which may underpin the known association of type I IFN with autoimmune diseases." (PMID 31024609, 2019). "Additionally, encephalitogenic inflammatory CD4+ T cells such as Th1, Th17, granulocyte macrophage colony-stimulating factor (GM-CSF)-producing CD4+ T-cells, and γδT-cells play very crucial roles in the initiation and propagation of neuroinflammation in autoimmune diseases such as MS." (PMID 30764536, 2019). "CD4 T cells recognise peptide antigens in the context of class II MHC molecules, and the mere presence of certain MHC alleles/allele groups may predispose an individual to autoimmune disease." (PMID 30984377, 2019).
autoimmune disease (continued). "Acute course of fatal autoimmunity in mice and humans with congenital Foxp3 defects also implies that an abundance of autoreactive CD4+Foxp3− cells and diversity of their TCRs may need to be re-examined to better understand the pathogenesis of autoimmune diseases." (PMID 31653839, 2019). "Additionally, antiviral therapies such as ganciclovir could potentially help to reduce the expansion of the CD28null CD4 T cells and hence possibly reduce the severity of many of the autoimmune diseases." (PMID 30984377, 2019). "However, whether the innate immunological function of CD4+ T lymphocytes contributes to the pathogenicity of autoimmune diseases remains unclear." (PMID 30755603, 2019). "In other autoimmune disorders such as rheumatoid arthritis, systemic lupus erythematosus, or type 1 diabetes, it has been shown that post-translational modifications of autoantigens can elicit the formation of CD4+ T cell responses as well as create neo-epitopes that are recognized by B cells." (PMID 29760702, 2018). "Thus, PD-1 agonists might be effective in limiting pathological CD4+ T cell responses in autoimmune diseases and allergies." (PMID 30201974, 2018). "Thus, it has been proposed that over-expression or high expression of PD-L1 could induce inactivation of T cells and help to treat autoimmune diseases, in which unwanted CD4+ T cells are abnormally activated." (PMID 29138509, 2017). "Thus, increased FASL expression may have a protective role in the case of autoimmune disease, where apoptosis of CD4+ T‐cells leads to decreased inflammation." (PMID 28250925, 2017). "Together, the animal modeling and human in vivo data linking vitamin D and calcitriol with effector T-cell apoptosis suggest that vitamin D may significantly influence the emergence of an autoimmune disease phenotype by increasing effector CD4+ T-cell sensitivity to extrinsic cell death signals." (PMID 25852682, 2015). "Finally, unanswered questions relating to vitamin D mechanisms in CD4+ T cells are highlighted to promote further research that may lead to a deeper understanding of autoimmune disease molecular etiology." (PMID 25852682, 2015). "Since CCR1 blockade is known to inhibit recruitment of not only macrophages but also CD4+ T-cells to nephritic kidneys in an autoimmune disease mouse model, we were concerned that the phenotype observed in our experiments could be attributed to affects on the T-cell populations rather than IMCs." (PMID 26183450, 2015). "As it was previously reported that Bregs lack suppressive capacity in autoimmune diseases, to further determine whether the regulatory properties of Bregs differ between HCs and GCs, sorted CD4+CD25− effector T cells from HCs were co-cultured with autologous Bregs or Bregs from GCs." (PMID 26378021, 2015). "Collectively, the data demonstrating calcitriol enhancement of Ikzf2, FOXP3, and Ctla4 gene expression suggest that vitamin D may significantly influence the emergence of an autoimmune disease phenotype by increasing CD4+CD25+FoxP3+ Treg cells and/or their suppressive function." (PMID 25852682, 2015). "These disturbances could be elucidated by the fact that, by preventing the activation of autoreactive pathogenic cells, CD4+CD25+FOXP3+ regulatory T lymphocytes (Tregs) have a critical role in the maintenance of self-tolerance and thus in the prevention of autoimmune disease." (PMID 25653477, 2015). "The significance of the Foxp3KOOX40CD30KO mice with a global defect in Tregs is that it suggests that blocking OX40 alone, or in combination with CD30, would be very effective treatment for wide number of CD4 driven autoimmune diseases without rendering patients susceptible to infection." (PMID 24782861, 2014).
autoimmune disease (continued). "In many autoimmune disorders, e.g., juvenile idiopathic arthritis, psoriatic arthritis, multiple sclerosis, systemic lupus erythomatosus, autoimmune hepatitis, and type-1 diabetes, the numbers and suppressive activity of circulating CD4+CD25+ Treg cells dramatically reduced." (PMID 25152867, 2014). "Although IL-17 was identified more than 15 years ago as a product of CD4+ T cells, it was only recently proven that IL-17 is preferentially produced by a subset of T cells, specifically Th17, which have been shown to be very important in the pathogenesis of autoimmune disease." (PMID 25045213, 2014). "Given that CD4+ T/T-cell lymphopenia can induce LIP to cause autoimmune diabetes in NOD mice, it further supports the hypothesis that premature CD4+ T cell aging can cause autoimmune disease." (PMID 24586733, 2014). "This tight balance between regulatory and effector reactions depends on the ability of CD4+ T cells to modulate distinct pathways within large molecular networks, since dysregulated CD4+ T cell responses may result in chronic inflammatory and autoimmune diseases." (PMID 25364738, 2014). "Thus, further work will be necessary to determine whether a feedback loop exists between BAFF-producing neutrophils and IFNγ-producing CD4+ T cells in the recruitment of neutrophils in autoimmune disease." (PMID 25010693, 2014). "Finally, we addressed whether MSCs could affect the generation of Th1, Th17 and CD4+CD25+Foxp3+ Treg cells in a T-cell-mediated autoimmune disease such as EAE." (PMID 23734780, 2013). "It has been suggested recently that minor perturbations in the number or function of Tregs may be permissive for the development of autoimmune disease, allowing differentiation and proliferation of low affinity self-reactive CD4 T cells that have escaped thymic deletion." (PMID 24147013, 2013). "It remains to be clarified whether naïve CD4+ T cells might be of regulatory phenotype and nature in the CNS, and could therefore provide an opportunity for a novel therapeutic approach in MS or other autoimmune diseases." (PMID 21978405, 2011). "In line with this, direct TLR4 stimulation in CD4 T lymphocytes has been shown to promote T helper 17 responses and to aggravate the evolution of autoimmune diseases, indicating that the observed decrease in IL-17 production may indeed contribute to the suppressed arthritis in TLR4 defective mice." (PMID 21858160, 2011). "Therefore, we hypothesize that gene transduction of naive CD4+ T cells with FoxP3 and Bcl-xL can induce the generation of highly reactive Tregs, which may be used in the treatment of autoimmune disease." (PMID 20384988, 2010). "Therefore, we tested the hypothesis that co-transduction of CD4+ T cells with both FoxP3 and Bcl-xL will generate highly reactive Tregs that can be used to prevent autoimmune disease." (PMID 20384988, 2010). "Therefore, their replacement with CD4+CD25+ Treg cells obtained from normal donors or in vitro expanded autologous functional CD4+CD25+ Treg represents a new paradigm for immunotherapy of autoimmune diseases." (PMID 19543393, 2009). "In addition to IPEX, many more common polygenic autoimmune disorders, including multiple sclerosis, type 1 diabetes, are hypothesized to have abnormalities in CD4+CD25high regulatory T cell function." (PMID 19046457, 2008). "The present study was performed to investigate whether the progression of organ-specific autoimmune diseases could be reduced more markedly by accumulating chemokine receptor-expressing CD4+CD25+ regulatory T cells efficiently in target organs in MRL/MpJ-lpr/lpr (MRL/lpr) mice." (PMID 17284325, 2007). "CD4+CD25+FoxP3+ Tregs are essential for maintaining peripheral tolerance, and their depletion leads to spontaneous autoimmune disease in both mice and humans." (PMID 40852720, 2025). "Tumors can prompt CD4+ T cells to transform into CD4+CD25+FOXP3+ Treg cells, crucial in the progression of autoimmune diseases and tumors." (PMID 41438510, 2025).